CD47 (CD47 molecule)
Diseases named in the same sentence as CD47 in open-access papers (continued):
Sharing a sentence is not in itself a finding about the gene and the disease.
Sepsis (4 papers, 2020 to 2025). Sepsis is defined as life-threatening organ dysfunction caused by a dysregulated host response to infection. "On the other hand, CD47 expression is upregulated during infection, and the increase is more pronounced during sepsis." (PMID 40185975, 2025). "The SIRPα-CD47 pathway is an attractive potential therapeutic target in sepsis, particularly in the context of neutrophils and other immune cells." (PMID 40568588, 2025). "Nevertheless, our translational experiments using a specific peptide targeting the Siglec-G/CD47 interaction demonstrated the physiological significance of this mechanism in sepsis, highlighting its potential impact on disease progression." (PMID 40568588, 2025). "To address this, we developed C11, a novel peptide specifically designed to disrupt the Siglec-G/CD47 interaction on B-1a cells in sepsis." (PMID 40568588, 2025). "CD47 was decreased in platelets of septic mice which on the other hand can increase the mortality of mice suffering sepsis." (PMID 33204219, 2020). "We first confirmed that B-1a cells express Siglec-G and CD47 under normal and in sepsis conditions." (PMID 40568588, 2025). "These structural properties of CD47 further support the observed Siglec-G/CD47 interaction, suggesting a previously unrecognized regulatory mechanism that contributes to B-1a cell depletion during sepsis." (PMID 40568588, 2025). "The effects of C11 may extend beyond preserving B-1a cells to the regulation of neutrophil function through SIRPα-CD47 signaling during sepsis." (PMID 40568588, 2025). "CD47 was highly expressed in newly emerging myeloid cells at sepsis onset." (PMID 40185975, 2025). "In this study, we hypothesize that Siglec-G/CD47 interactions on B-1a cells enhance neutrophil-mediated B-1a cell trogocytosis, thereby contributing to B-1a cell depletion in sepsis." (PMID 40568588, 2025). "Thus, by blocking the Siglec-G/CD47 interaction, C11 aims to prevent neutrophil-mediated trogocytosis of B-1a cells, thereby preserving their immunomodulatory function and mitigating sepsis-induced inflammation." (PMID 40568588, 2025). "Previous studies have confirmed that CD47, Lcn2, and Sphk1 were involved in the sepsis process." (PMID 33204219, 2020). "Considering the high expression of CD47, which is widespread in almost all immune cells and thus it is regarded as a new immune checkpoint molecule and a novel target in cancer immunotherapy studies, we speculated that CD47 may play an important role in adaptive immunosuppression in sepsis." (PMID 40185975, 2025). "In addition, it has recently been reported that both LGALS9 and CD47 are co-inhibitory molecules, suggesting the LGALS9-CD47 pair might also contribute to the enhanced immunosuppressive effect of Tregs in elderly patients with sepsis." (PMID 38909272, 2024). "Both the CD47 mRNA and protein expression levels were not significantly different in different cell populations, and no significant changes in different cell populations were found when sepsis occurred." (PMID 40185975, 2025). "Indeed, our targeted intervention to block the Siglec-G/CD47 interaction and inhibit neutrophil-mediated trogocytosis did not fully restore B-1a cell numbers in sepsis, further supporting the idea that multiple mechanisms contribute to B-1a cell depletion during sepsis." (PMID 40568588, 2025).
urothelial carcinoma (4 papers, 2022 to 2023). A malignant neoplasm derived from the transitional epithelium of the urinary tract (urinary bladder, ureter, urethra, or renal pelvis). "Analyses using immunofluorescence and fluorescence-activated cell technology confirmed that CD47 is widely expressed in most urothelial carcinoma cells, and CD44+ CSCs have higher CD47 expression level compared to subset of CD44−tumor cells." (PMID 35903544, 2022). "The areas without ICG-anti-CD47 fluorescence were identified as normal urothelial carcinoma." (PMID 36937442, 2023).
uveal melanoma (4 papers, 2019 to 2024). A melanoma derived from melanocytes of the uveal tract. "Uveal melanoma can evade immune surveillance via multiple mechanisms, such as inhibitory checkpoint programmed cell death ligand 1 (PD-L1), cluster of differentiation 47 (CD47), and cluster of differentiation 200 (CD200)." (PMID 38732371, 2024). "Uveal melanoma can evade immune surveillance via multiple mechanisms such as the expression of inhibitory checkpoint programmed cell death ligand 1 (PD-L1), cluster of differentiation 47 (CD47), cluster of differentiation 200 (CD200)." (PMID 35741122, 2022).
age-related macular degeneration (3 papers, 2018 to 2021). Age-related loss of vision in the central portion of the retina (macula), secondary to retinal degeneration. "Additionally, genetic variants of CFH are strongly associated with age-related macular degeneration (AMD), and CFH has been shown to inhibit the anti-inflammatory activity of CD47." (PMID 32157596, 2020). "Indicative of the importance of this immunosuppressor function is the recent proof that the minor haplotype of chromosome10q26, a strong risk factor for the development of age-related macular degeneration (AMD), results in inhibition of CD47-signalling leading to chronic subretinal inflammation." (PMID 34884622, 2021). "The authors showed that FH binding to mononuclear phagocytes inhibits the CD47-mediated homeostatic elimination of mononuclear phagocytes, resulting in non-resolving inflammation within the sub-retinal space, which may be involved in the pathogenesis of age-related macular degeneration (AMD)." (PMID 29616045, 2018).
Anxiety (3 papers, 2014 to 2025). Intense feelings of nervousness, tension, or panic often arise in response to interpersonal stresses. "Notably, neuronal CD47 causes behavioral disinhibition, which is characterized by reduced anxiety-like behaviors and increased exploratory activity compared to wild-type mice." (PMID 40140948, 2025). "Since increased center time was only seen in the earlier part of the experimental period, it is possible that a deficiency in CD47 may lead to decreased anxiety in a novel environment in these mice." (PMID 24586890, 2014). "Anxiety-like behaviors of CD47 KO mice were evaluated in the open field, light/dark transition, and elevated plus-maze tests." (PMID 24586890, 2014). "Notably, CD47-overexpressing mice spent more time in the center of the open field arena, suggesting behavioral disinhibition and reduced anxiety." (PMID 40140948, 2025). "Thus, CD47 overexpression results in specific behavioral disinhibition and decreased anxiety." (PMID 40140948, 2025). "Additionally, in the open field test, CD47 KO mice stayed significantly longer in the center of the field during the earlier part of the experimental period, but not over the entire experimental period, indicating that the mutants show decreased anxiety-like behavior in a novel environment." (PMID 24586890, 2014).
Clear Cell Renal Cell Carcinoma (3 papers, 2022 to 2025). "Here, the clinicopathological correlation with CD47 expression in clear cell renal cell carcinoma (ccRCC) was explored." (PMID 36291980, 2022).
colorectal adenocarcinoma (3 papers, 2021). The most common type of colorectal carcinoma. "Association between CD47 expression, clinical characteristics and prognosis in patients with different malignancies, including advanced non-small cell lung cancer, gastric cancer, colorectal adenocarcinoma and pancreatic neuroendocrine tumor has been explored." (PMID 34717705, 2021). "CD47 expression also has correlation with adverse clinicopathologic features and an unfavorable prognosis in colorectal adenocarcinoma." (PMID 34717705, 2021). "However, the prognostic significance of CD47 expression in colorectal adenocarcinoma (CRA) has not yet been clarified." (PMID 33917794, 2021).
Crohn disease (3 papers, 2020 to 2024). A gastrointestinal disorder characterized by chronic inflammation involving all layers of the intestinal wall, noncaseating granulomas affecting the intestinal wall and regional lymph nodes, and transmural fibrosis. "To examine CD47 level in human intestinal epithelium under IBD condition, we collected colonoscopic biopsies (6 each) from Crohn’s diseases (CD), ulcerative colitis (UC) patients and subjects without chronic intestinal inflammatory condition." (PMID 32576895, 2020).
encephalitis (3 papers, 2007 to 2022). An acute inflammatory process affecting the brain parenchyma. "Blockade of CD47 ameliorates encephalitis by suppressing IL-1-mediated infiltration of Th17 cells and CD47 knockout mice are refractory to development of experimental autoimmune encephalomyelitis." (PMID 34068752, 2021).
esophageal cancer (3 papers, 2020 to 2022). A primary or metastatic malignant neoplasm involving the esophagus. "Recent studies have also described elevated CD47 levels in tissue-infiltrating NK cells and CD8+ T cells in esophageal carcinoma patients, but the impact of anti-CD47 treatments on lymphocyte and particularly effector T cells in patients has not been extensively documented." (PMID 35664753, 2022).
experimental autoimmune encephalomyelitis (3 papers, 2021 to 2023). An autoimmune demyelinating disease of the central nervous system that is produced experimentally in animals by the injection of homogenized brain or spinal cord in Freund's adjuvant. "In experimental autoimmune encephalomyelitis (EAE) mouse models, pharmacological and genetic inhibition of CD47 in the induction phase reduces disease severity." (PMID 37368493, 2023).
Glucose intolerance (3 papers, 2015 to 2022). Glucose intolerance (GI) can be defined as dysglycemia that comprises both prediabetes and diabetes. "In mouse studies, protein tyrosine kinase 2 beta (PTK2B) was found to play a critical role in the differentiation of beige adipocytes, CD47–/– knockout resulted in resistance to insulin desensitisation, glucose intolerance and diet-associated weight gain." (PMID 36151087, 2022). "Glucose tolerance and insulin sensitivity were significantly improved in HF-fed CD47-/- mice as compared to HF-fed WT mice, suggesting that CD47 deficiency protects mice from diet-induced glucose intolerance and insulin resistance." (PMID 25747123, 2015). "Aged CD47-null mice were protected from decrease in angiogenesis, blood flow, high fat diet (HFD)-induced weight gain, glucose intolerance and insulin resistance." (PMID 32679764, 2020).
Hepatic steatosis (3 papers, 2020 to 2025). Steatosis is a term used to denote lipid accumulation within hepatocytes. "Previous studies have shown that CD47 deficiency can prevent aging-induced glucolipid metabolic dysfunction, thereby alleviating hepatic steatosis." (PMID 40630093, 2025). "We show that CD47 deficiency significantly attenuated body weight gains and subcutaneous fat accumulation, while severely worsening hepatic steatosis and fibrosis induced by prolonged HFD consumption." (PMID 32158445, 2020). "In summary, CD47 regulates mitochondrial dynamics and function, and its deficiency appears to have protective effects on mitochondrial activity, potentially mitigating liver steatosis." (PMID 40630093, 2025). "Histological analysis was performed to determine whether CD47 deficiency may promote the development of fatty liver disease." (PMID 32158445, 2020). "This seems to contradict previous research findings, CD47 regulates the development of MASLD/MASH through various pathways, and multiple stimuli can aggravate hepatic steatosis via the NF-kB signaling pathway." (PMID 40630093, 2025). "Collectively, these findings suggest that CD47, by integrating signals from TSP1, NF-κB, and immune evasion pathways, plays a complex and context-dependent role in aging-related hepatic steatosis and fibrosis." (PMID 40630093, 2025).
HIV-1 infection (3 papers, 2018 to 2024). The type species of lentivirus and the etiologic agent of acquired immunodeficiency syndrome (AIDS). "Enhanced PD-1, a marker of NK exhaustion and dysfunction was found elevated in CD47-deficient NK cells during LCMV Cl-13 infection similar to that reported in chronic HIV-1 infection." (PMID 30643501, 2018).
immune deficiency (3 papers, 2015 to 2021). "As an example, net suppression of the CD47–SIRPα interaction might be associated with immune deficiency, leading to increased susceptibility of SLE patients to infection and cancer." (PMID 34068752, 2021).
injury (3 papers, 2021 to 2024). Damage inflicted on the body as the direct or indirect result of an external force, with or without disruption of structural continuity. "The expression of the CD47 epitope was found to correlate positively with the American Spinal Injury Association (ASIA) impairment scale." (PMID 39703513, 2024).
intracerebral hemorrhage (3 papers, 2020 to 2023). A cerebrovascular disorder characterized by bleeding into one or both cerebral hemispheres including the basal ganglia and the cerebral cortex. "In another pig model of intracerebral hemorrhage, Zhou and colleagues identified that brain tissue displayed an increased percentage of CD47 expression in both white and gray matter." (PMID 38125492, 2023). "Additionally, anti-CD47 treatment has been demonstrated to enhance hematoma clearance and improve prognosis in the experimental intracerebral hemorrhage model (swine and rats model)." (PMID 35281006, 2022). "The medication Deferoxamine could reduce the expression of CD47 after intracerebral hemorrhage, leading to an acceleration of hematoma removal by promoting erythrophagocytosis." (PMID 35281006, 2022).
laryngeal carcinoma (3 papers, 2021 to 2024). Carcinoma that arises from the laryngeal epithelium. "microRNA-133a is able to target the CD47 protein that inhibits the proliferation, migration, and infiltration of laryngeal carcinoma cells." (PMID 34189144, 2021). "Upregulated miR-133a could inhibit proliferation, invasion, and migration and promote cell apoptosis in laryngeal carcinoma by targeting CD47." (PMID 38439112, 2024). "Others indicated that the suppressive effect of this miRNA in laryngeal cancer might be related to the targeting of CD47, a transmembrane protein widely expressed in tumor cells." (PMID 34439138, 2021).
Lewis lung carcinoma (3 papers, 2016 to 2023). "Conversely, treatment with the CD47 ligand thrombospondin-1 was recently reported to inhibit proliferation, sphere formation, and expression of stem cell transcription factors in Lewis lung carcinoma cells, and CD47 shRNA knockdown blocked this activity." (PMID 26840086, 2016).
mesothelioma (3 papers, 2010 to 2023). A usually malignant and aggressive neoplasm of the mesothelium which is often associated with exposure to asbestos. "To study the expression of CD47 in response to DNA damage in tumors, we used AB12 mesothelioma cells." (PMID 36882648, 2023). "We further show that CD47 expression is upregulated in livers harvested from mice treated with the DNA-damage inducing agent Diethylnitrosamine (DEN) and in cisplatin-treated mesothelioma tumors." (PMID 36882648, 2023). "Among the surface markers known to be expressed by mesothelioma cell lines, our cell cultures were strongly positive for CD46, CD47, CD56 and CD63, while showed a variable positivity for CD140b and CD141." (PMID 20175889, 2010). "Our cell cultures were strongly positive for CD46, CD47, CD56 and CD63 and were also strongly positive for some markers never described before in mesothelioma cell lines, including CD55, CD90 and CD99." (PMID 20175889, 2010).
metastatic melanoma (3 papers, 2023 to 2025). A melanoma that has spread from its primary site to another anatomic site. "Given that high expression of checkpoints PD-1, PD-L1, VISTA, SIRPα, and CD47 expression associated with anti-PD-1 response in our cohort, it remains to be investigated whether combination therapy with myeloid checkpoint blockade can overcome anti-PD-1 resistance in metastatic melanoma." (PMID 40897819, 2025).
myelofibrosis (3 papers, 2018 to 2025). A partial or complete replacement of the bone marrow stroma by fibrous tissue. "Moreover, Dr. Boasman reported that the combination of a Jak inhibitor (ruxolitinib) and an anti-CD47 antibody increased the expression of calreticulin, signaling a much stronger prophagocytic message in cells derived from primary myelofibrosis patients." (PMID 38464520, 2024). "High CD24 (not CD47) protein expression was detected in BM neutrophils from mouse models of PV, ET or secondary (post-ET) myelofibrosis." (PMID 40373279, 2025).
myeloid sarcoma (3 papers, 2012 to 2025). A tumor mass composed of myeloblasts or immature myeloid cells. "In this model, murine histiocytic sarcomas, equivalent to human myeloid sarcomas, emerged at the injection site 30–50 days after cell implantation and consisted of tightly packed monotypic cells that were CD48+, CD47+ and Mac1+, with low or absent expression of other hematopoietic lineage markers." (PMID 22952867, 2012).
myocardial ischemia (3 papers, 2018 to 2025). A disorder of cardiac function caused by insufficient blood flow to the muscle tissue of the heart. "Following myocardial ischemia and reperfusion, inhibition of integrin-associated protein CD47 with blocking antibodies increased the clearance of dead myocytes by cardiac phagocytes and increased the resolution of cardiac inflammation." (PMID 31766552, 2019). "CD47+ EVs are enriched in miR-320a, which has been associated with cardiac ischemia/perfusion injury by targeting heat shock protein-2032." (PMID 29416092, 2018).
ovarian clear cell cancer (3 papers, 2015 to 2024). An invasive malignant neoplasm that arises from the ovary and is characterized by a predominance of clear and hobnail malignant epithelial cells. "Expression of CD44, CD47 and c-met in ovarian clear cell carcinoma (OCCC)." (PMID 25658794, 2015).
papillary thyroid carcinoma (3 papers, 2019 to 2024). "Papillary thyroid carcinomas exhibited strong associations between survival and expression of CD47 or IFT57." (PMID 39201643, 2024). "Conversely, transient overexpression of IFT57 by plasmid transfection resulted in a lower increase in CD47 mRNA expression in MDA-T68 follicular variant of papillary thyroid carcinoma cells than induced by transfection with the empty vector." (PMID 39201643, 2024). "Of the 67 annotated genes with available TCGA papillary thyroid carcinoma data, 46 had significant coexpression with CD47 in the tumors." (PMID 39201643, 2024). "CD47 ranked first for coexpression with IFT57 mRNA in papillary thyroid carcinomas, and higher expression of both genes correlated with significantly improved overall survival." (PMID 39201643, 2024). "CD47 was top-ranked for IFT57 mRNA coexpression in papillary thyroid carcinomas, with a Spearman coefficient r = 0.62." (PMID 39201643, 2024). "Of the 41 overlapping genes, 11 were significantly correlated with mRNA expression of both CD47 and IFT57 in TCGA papillary thyroid carcinomas, but only 5 of the latter were consistent with the direction of change in the IFT57 knockdown cell lines." (PMID 39201643, 2024).